HSP90AB1 (heat shock protein 90 alpha family class B member 1)
Diseases named in the same sentence as HSP90AB1 in open-access papers (continued):
Sharing a sentence is not in itself a finding about the gene and the disease.
psoriasis (3 papers, 2020 to 2026). An autoimmune condition characterized by red, well-delineated plaques with silvery scales that are usually on the extensor surfaces and scalp. "Consistent with previous results, high expression levels of CTCF and HSP90AB1 were demonstrated in psoriasis." (PMID 41114929, 2026). "The previous results hinted that HSP90AB1 might be an important molecular functioning in the development of psoriasis." (PMID 41114929, 2026). "To further understand how NB could achieve its therapeutic functions in psoriasis, we performed nascent proteomics and identified HSP90AB1 as a potential key target." (PMID 41114929, 2026). "Sequencing data from GEO database (GSE13355, GSE114286, and GSE53431) revealed that HSP90AB1 expression was notably increased in lesion skin from psoriasis patients compared to the normal donates and UV treatment could lower the expression." (PMID 41114929, 2026).
Arthritis (2 papers, 2019 to 2023). Inflammation of a joint. "HSP90AB1 may inhibit the upregulation of MMP-13 from mitigating transitional degradation of articular cartilage in arthritis." (PMID 37779906, 2023).
Cirrhosis (2 papers, 2019 to 2022). A chronic disorder of the liver in which liver tissue becomes scarred and is partially replaced by regenerative nodules and fibrotic tissue resulting in loss of liver function. "HSP90AB1 is also associated with HCC, and it may be involved in the progression from cirrhosis to HCC." (PMID 36211823, 2022).
colorectal tumor (2 papers, 2016 to 2019). "This association between rs2282151 and CRC is probably mediated by the expression of the inflammatory-related gene HSP90AB1, which is upregulated in colorectal tumor tissues." (PMID 27756247, 2016). "Then we compared the difference of mRNA expression levels of HSP90AB1 in colorectal tumor and paired normal samples using online data sources." (PMID 27756247, 2016).
Hypertension (2 papers, 2024 to 2025). The presence of chronic increased pressure in the systemic arterial system. "The results indicate that in the Ang II-induced hypertension group, the expression levels of TNF, NFKB1, MAPK3, PTGS2, and RELA were markedly elevated compared to the control group, while the expression levels of HSP90AA1, HSP90AB1, PPARG, SIRT1, MAPK1, and PRKCA were significantly decreased." (PMID 39592923, 2024).
liver fibrosis (2 papers, 2021 to 2023). "By mapping the candidate targets to the 66 known genes associated with hepatic fibrosis obtained from OMIM and DrugBank, 10 co-targets were found, including HSP90AA1, PPARG, MAPT, HSP90AB1, STAT1, and PPARA." (PMID 33510287, 2021). "The key targets included 8 co-targets, including HSP90AA1, PPARG, HSP90AB1, STAT1, etc., which play pivotal roles in the pathogenesis of liver fibrosis." (PMID 33510287, 2021). "Our results demonstrated that SCST could target HSP90AA1, PPARG, HSP90AB1, STAT1, etc., further regulating the PPARG signalling pathway that is closely related to liver fibrosis, and the flavonoids and phenylpropanoids of SCST are important ingredients against hepatic fibrosis." (PMID 33510287, 2021).
osteoporosis (2 papers, 2024 to 2026). A condition of reduced bone mass, with decreased cortical thickness and a decrease in the number and size of the trabeculae of cancellous bone (but normal chemical composition), resulting in increased fracture incidence. "Additionally, the heat shock protein 90β (HSP90Β), encoded by HSP90AB1, has been found to promote the expression of osteoclasts through the NF‐κB signaling pathway, and genetic deletion of HSP90AB1 has been shown to alleviate bone loss in rats with osteoporosis." (PMID 38990187, 2024).
prostate adenocarcinoma (2 papers, 2019 to 2023). "The canonical chaperone Hsp90 isoforms HSP90AA1 and HSP90AB1 were also found to be upregulated in several cancers including pancreatic adenocarcinoma, thymoma, and prostate adenocarcinoma, respectively." (PMID 31814876, 2019).
rheumatoid arthritis (2 papers, 2019 to 2023). A chronic, systemic autoimmune disorder characterized by inflammation in the synovial membranes and articular surfaces. "Zhu et al25 have identified a potential role of HSP90AB1 in the genetic susceptibility to rheumatoid arthritis." (PMID 31124601, 2019).
schizophrenia (2 papers, 2012 to 2023). A major psychotic disorder characterized by abnormalities in the perception or expression of reality. "The central nervous system of patients with schizophrenia undergoes autoimmune-mediated processes, which increase the antibody responses to HSP70 and HSP90AB1 proteins." (PMID 37966892, 2023).
Sepsis (2 papers, 2023 to 2025). Sepsis is defined as life-threatening organ dysfunction caused by a dysregulated host response to infection. "The logistic regression algorithm identified 8 genes (VDAC1, HSPA8, SOD1, HSPA9, TXN, NDUFS3, HSP90AB1, SNCA), among which 6 genes were closely correlated with the onset of sepsis-induced ALI (p < 0.05)." (PMID 40694561, 2025). "Similarly, our study showed that IFN-γ signaling pathway proteins (ACTG1, HSP90AB1, and VCAM1) were significantly higher in patients with HLH than in patients with sepsis." (PMID 37653176, 2023).
acute myeloid leukemia (1 paper, 2023). Acute myeloid leukemia (AML) is a group of neoplasms arising from precursor cells committed to the myeloid cell-line differentiation. "Exceptionally, SCAND2 and MZF1(ZSCAN6) gene expression was higher in acute myeloid leukemia (LAML), while the expression levels of HSP90AA1 and HSP90AB1 genes were lower, compared with paired normal tissues." (PMID 36982267, 2023).
brain tumour (1 paper, 2024). "Of note, ANXA1, ANXA2, GNAS, HSP90AA1, HSP90AB1 and PSMD2, were highly abundant in EVs captured from GBM neurosurgical aspirates and in Pre-OP GBM uEVs here, implicating a potential brain tumour diagnostic utility for TRiC subunits and their interacting partners." (PMID 38212481, 2024).
breast tumor (1 paper, 2022). "The additionof Col1 increased cell proliferation as well as the drug sensitivityof the bioprinted tumors associated with a downregulation of HSP90AB1.Overall, these results demonstrate the great potential of these bioinksfor fabricating breast tumor models by bioprinting." (PMID 35735173, 2022).
Crohn disease (1 paper, 2022). A gastrointestinal disorder characterized by chronic inflammation involving all layers of the intestinal wall, noncaseating granulomas affecting the intestinal wall and regional lymph nodes, and transmural fibrosis. "Using the DGIdb database, four key NLRP3 inflammasome-related genes (APP, HSP90AB1, NFKB and TLR4) were further selected as potential druggable targets for Crohn’s disease treatment." (PMID 36685554, 2022).
endometriosis (1 paper, 2020). The growth of functional endometrial tissue in anatomic sites outside the uterine body. "Five genes (ANXA4, CDA, CDK10, DST, and HSP90AB1) from the catalogue were reported to be associated with endometriosis at two omics levels, for example ANXA4 gene at transcriptomics and ANXA4 at proteomics level." (PMID 32474803, 2020).
gout (1 paper, 2022). A condition characterized by painful swelling of the joints, which is caused by deposition of urate crystals. "We found bisacumol, campesterol, and stigmasterol to be the main turmeric compounds that exerted a marked effect on gout treatment by targeting protein processing in the endoplasmic reticulum through the HSPA1B, HSP90AB1, and STUB1 proteins." (PMID 36276864, 2022). "Our PPI analysis showed that turmeric and corn silk influence gout through their impact on a complex biological network, including HSPA1B, HSP90AB1, STUB1, CTNNB1, YWHAG, and YWHAZ." (PMID 36276864, 2022). "These active ingredients may target protein processing in the endoplasmic reticulum through HSPA1B, HSP90AB1, and STUB1 proteins and play a significant role in treating gout." (PMID 36276864, 2022). "Candidate targets of turmeric for gout were HSPA8, VCP, HSP90AB1, HSPA5, HSPA1B, NFKB1, and STUB1." (PMID 36276864, 2022).
Immunodeficiency (1 paper, 2023). Failure of the immune system to protect the body adequately from infection, due to the absence or insufficiency of some component process or substance. "Notably, from the PPI network, we observed that TNF, STAT3, TLR4, PIK3R1, and HSP90AB1 were significant targets for GAC intervention in CY-induced immunodeficiency." (PMID 37853057, 2023).
Impaired glucose tolerance (1 paper, 2018). An abnormal resistance to glucose, i.e., a reduction in the ability to maintain glucose levels in the blood stream within normal limits following oral or intravenous administration of glucose. "In the present study knockdown of Hsp90ab1 reduced expression in the skeletal muscle and this was associated with improvement in metabolic flexibility, as systemic administration of ASO to Hsp90ab1 significantly improved impaired glucose tolerance in DIO mice." (PMID 29434648, 2018).
liver diseases (1 paper, 2021). "The co-targets are closely related to liver diseases, and in the degree order, the top four included heat shock protein 90AA1 (HSP90AA1), peroxisome proliferator-activated receptor G (PPARG), heat shock protein 90AB1 (HSP90AB1), and signal transduction and transcriptional activator 1 (STAT1)." (PMID 33510287, 2021).
male infertility (1 paper, 2021). The inability of the male to effect fertilization of an ovum after a specified period of unprotected intercourse. "HSP90AB1 interacted with the catalytic domain of Kdm3a, that mutant Kdm3a can cause male infertility in mice." (PMID 34580317, 2021).
nephrolithiasis (1 paper, 2025). The presence of a calculus in the pelvis of the kidney; this is most often composed of mineral salts and proteins. "HSP90AB1 showed low expressed in the validation set GSE117518 for nephrolithiasis, while the other two diagnostic genes were highly expressed, although the p values were not significant." (PMID 40245021, 2025). "For nephrolithiasis biomarkers, the three pivotal genes, HSP90AB1 (AUC=0.857), HSPA5 (AUC=0.845), and STUB1 (AUC=0.872), showed strong predictive performance." (PMID 40245021, 2025).
neuroblastoma (1 paper, 2021). Neuroblastoma (NB) is the most common solid, extracranial childhood tumor. "Commercially available pharmacological inhibitors of SDHA (malonate), HSP90AB1 (geldanamycin), and VDAC3 (TRO19622) were used for functional evaluation of the TDP-43 genetic-interacting loci in N2a neuroblastoma cells." (PMID 33803845, 2021).
retinitis pigmentosa (1 paper, 2024). Retinitis pigmentosa (RP) is an inherited retinal dystrophy leading to progressive loss of the photoreceptors and retinal pigment epithelium and resulting in blindness usually after several decades. "Effect of knockdown of Hsp90ab1 in retinitis pigmentosa cones in vivo." (PMID 38727583, 2024).
Salmonella Infections (1 paper, 2025). Infections with bacteria of the genus SALMONELLA. "The “Salmonella Infection” pathway includes HSP90AB1, IRAK4, and PIK3C2A, focusing on host-pathogen interactions and inflammation." (PMID 40621499, 2025).
sarcoma (1 paper, 2023). A usually aggressive malignant neoplasm of the soft tissue or bone. "Multiple genes were downregulated (p < 0.05) in sarcoma tumors, including HSP90AB1, IGHA1, INSM1, IRF5, MAP2K2, and SEH1L." (PMID 37445737, 2023).
sleeping sickness (1 paper, 2023). "HBA1, UBE2I, CSNK2A1, RRP12, and HSP90AB1 were highly enriched in African trypanosmiasis (sleeping sickness) than in the dengue viral infection pathway." (PMID 37498862, 2023).
squamous cell carcinoma (1 paper, 2023). A carcinoma arising from squamous epithelial cells. "A previous study revealed significant differences in HSP90AB1 mRNA expression levels between squamous cell carcinomas and healthy control tissue." (PMID 38034011, 2023).
systemic lupus erythematosus (1 paper, 2019). An autoimmune multi-organ disease typically associated with vasculopathy and autoantibody production. "The aim of our study was to assess the associations of HSP90AB1 copy number variations (CNVs) with systemic lupus erythematosus (SLE) risk and glucocorticoids (GCs) efficacy, as well as the relationship between HSP90AB1 single‐nucleotide polymorphisms (SNPs) and GCs efficacy." (PMID 31124601, 2019).
tauopathies (1 paper, 2022). "Here, we found that the gene expression of HSP90ab1 was significantly decreased after mossy cell overexpression of hTau N368; thus, HSP90ab1 could be a potential molecular target for tauopathies." (PMID 35355405, 2022).
cancer (134 papers, 2012 to 2026). A tumor composed of atypical neoplastic, often pleomorphic cells that invade other tissues. "HSP90AB1, a member of the Hsp90 family, is highly expressed in most cancers and is associated with prognosis." (PMID 41007338, 2025). "GA acts against BCC by targeting and inhibiting HSP90AB1, a protein associated with cancer aggressiveness." (PMID 38338469, 2024). "GA impacts SCC by inhibiting HSP90AB1, a protein associated with cancer’s invasiveness and aggressiveness." (PMID 38338469, 2024). "Proteins known to be associated with cancer or CSCs such as HSP90AB1, ALDH, vimentin, and AKR were upregulated in spheres and their expression was confirmed by western blot." (PMID 34794402, 2021). "STIP1 and HSP90AB1 are found associated with cell metastasis, apoptosis and other oncogenic functions in human cancer cells." (PMID 32194784, 2020). "HSP90 alpha, class B, member 1 (HSP90AB1) is a crucial facilitator of oncogene activation and cancer cell survival because the HSP90AB1 chaperone machinery in cancer cells can protect large amounts of mutated and overexpressed oncogenic proteins from misfolding and degradation." (PMID 37180757, 2023). "Importantly, the proteins encoded by HSP90AA1 and HSP90AB1 genes act in several pivotal roles in the cancer development through other relevant signaling pathways identified in this study, such as the ones involving the aryl hydrocarbon receptor (AhR), glucocorticoid receptor and nitric oxide (NO)." (PMID 33656060, 2021). "Conversely, HRP networks were characterized by the presence of Heat shock protein HSP90-alpha (HSP90AA1) and HSP90-beta (HSP90AB1), which are also important for cancer progression." (PMID 40136513, 2025). "HSP90AB1 protein participates in multiple cancer hallmarks, such as evasion of apoptosis, unlimited proliferation, as well as tissue invasion and metastasis." (PMID 38606171, 2024). "Elevated in numerous solid tumors, HSP90AB1 is believed to stimulate angiogenesis and facilitate cancer metastasis." (PMID 38280998, 2024). "Heat-shock family genes involved in HSF1 transactivation (e.g. HSPA1A, DNAJB1 and HSP90AB1) were also significantly enriched in this module, which has been shown previously to regulate cancer-mediated fibroblast activation." (PMID 36720863, 2023). "HSP90AB1 is upregulated in numerous solid tumors, and promotes the cancer progression via enhancing cancer cell proliferation, EMT, metastasis, and glycolysis." (PMID 37742009, 2023). "HSP90AA1, HSP90AB1, and HSP90B1 have been associated with a poor prognosis of tumors, and upregulation of TRAP1 promotes the growth and progression of various cancers." (PMID 37569852, 2023). "Numerous studies have demonstrated that HSP90AA1 and HSP90AB1 participate in tumorigenesis, and their overexpression promotes angiogenesis, metastasis, and differentiation of cancer cells." (PMID 36362498, 2022). "Transcripts of the two most abundant HSP90 members, HSP90AA1 or HSP90AB1, are elevated in 17 out of 21 major human cancers." (PMID 35311075, 2022). "It was unexpected that whole-genome proteomics analyses predicted Hsp90ab1, calreticulin and Ppib as tumor suppressors since they are highly expressed in many cancer tissues." (PMID 33859739, 2021). "Proteomics analysis revealed that heat shock protein 90 (Hsp90ab1), calreticulin (Calr) and peptidylprolyl isomerase B (Ppib), which are highly expressed intracellular proteins in many cancers, were enriched in MSC CM as atypical tumor suppressors." (PMID 33859739, 2021). "We also observed the selective inhibition of the MTT-based viability of MDA-MB-231 cancer cells by recombinant Hsp90ab1, Eno1, and Ubc proteins, compared to that of the three lines of human epithelial cells of breast origin (KTB6, KTB22, and KTB34)." (PMID 34830748, 2021). "In this study, we screened the target protein HSP90AB1 which is over-expressed in a large variety of cancer cells and belongs to highly conserved ATP-dependent molecular chaperone." (PMID 34217296, 2021).